DSE (dermatan sulfate epimerase)
Diseases named in the same sentence as DSE in open-access papers (continued):
Sharing a sentence is not in itself a finding about the gene and the disease.
glioblastoma (1 paper, 2018). The most malignant astrocytic tumor (WHO grade IV). "We found high DSE expression in several glioblastoma cell lines, and DSE expression directly mediated DS chain formation in glioblastoma cells." (PMID 29864158, 2018). "Knockdown of DSE suppressed the proliferation, migration, and invasion of glioblastoma cells." (PMID 29864158, 2018). "In an examination of DSE protein levels in human glioblastoma cell lines, mouse glioblastoma GL261 cells, and mouse brain cortex tissue, we found that 5 out of 7 human glioblastoma cell lines expressed relative high levels of DSE." (PMID 29864158, 2018).
Kyphoscoliosis (1 paper, 2025). An abnormal curvature of the spine in both a coronal (lateral) and sagittal (back-to-front) plane. "The musculocontractural Ehlers–Danlos syndrome (mcEDS), which is characterized by kyphoscoliosis, muscular hypotonia, skin hyperextensibility and fragility, joint hypermobility, and multiple joint dislocations, is caused by DSE or CHST14 mutations." (PMID 40141107, 2025).
lung carcinoma (1 paper, 2021). "To further validate these novel players in lung cancer cell migration, we selected five candidates—DSE, CPA4, FLNC, TUBB6, and BICC1—and the positive control CDH2, which were upregulated in fast cells and also associated with poor overall survival in NSCLC patients." (PMID 33934493, 2021).
cancer (15 papers, 2010 to 2025). A tumor composed of atypical neoplastic, often pleomorphic cells that invade other tissues. "The only upregulated FET-associated DEG was dermatan sulfate epimerase (DSE), which overexpression has been observed in several cancers and which associates with active angiogenesis, invasion, and proliferation." (PMID 39702541, 2024). "Dermatan sulfate epimerase 1 (DSE) is overexpressed in many types of cancer, and CS/DS chains mediate several growth factor signals." (PMID 29864158, 2018). "The involvement of DS-epi1 in NC migration in Xenopus embryos prompted us to investigate a potential link between DSE expression and tumorigenic properties in two human NC-derived cancers." (PMID 27101845, 2016). "The ratio of dermatan sulfate to chondroitin sulfate is increased in cancer and thus the relative increase of dermatan sulfate should be attributed to DSE increased expression observed in the present work." (PMID 20929582, 2010). "We found that JW-7-52-1, GW843682, and MG-132 may be effective as drugs for targeting CHST, CHSY3, and DSE, respectively, based on the Genomics of Drug Sensitivity in Cancer (GDSC) database." (PMID 35326589, 2022). "Finally, two genes that were up-regulated by RNASET2 were also selected for validation: LMCD1, belonging to the category of the LIMD1 tumor suppressor gene, and DSE (dermatan sulfate epimerase), whose protein product elicits specific cytotoxic T lymphocytes responses in cancer patients." (PMID 21646684, 2011).
tumor (11 papers, 2010 to 2025). "Furthermore, high DSE expression was associated with advanced tumor grade and poor survival." (PMID 29864158, 2018). "By integrating both single-cell and bulk RNA-seq data, we identified six key prognostic genes (BOP1, CTBP1, DSE, PMSD10, SRPK1, and HACD4), which were associated with poor prognosis and tumor cell proliferation." (PMID 40963856, 2025). "The analysis revealed that risk genes (BOP1, CTBP1, DSE, SRPK1, and PMSD10) were significantly upregulated in tumor samples, whereas the protective gene HACD4 was highly expressed in normal samples." (PMID 40963856, 2025). "The identification of prognostic markers through Cox regression and Lasso regression further highlighted the significant role of the risk genes BOP1, CTBP1, DSE, SRPK1, and PMSD10, which were upregulated in high mRNAsi tumor cells." (PMID 40963856, 2025). "Immunohistochemical analysis of Ki-67 expression in tumors showed that overexpression of DSE significantly inhibited Ki-67 expression in tumor tissues, while knockdown of DSE significantly promoted Ki-67 expression." (PMID 37833287, 2023). "In fact, the DSE gene codifies an glycosaminoglycan isomerase, acting as a tumor-rejection antigen and with the potential to stimulate anti-tumoral immunoreactivity." (PMID 36009354, 2022). "Western blots and the immunohistochemistry of the excised tumors confirmed the expression of DSE in tumor tissue." (PMID 29864158, 2018). "The expression of three genes (FAM55C, GALNT3, and DSE) was significantly (p < 0.05) lower in tumor tissues than in normal tissues." (PMID 29848370, 2018). "In addition, overexpression of DSE promoted the overexpression of tumor killer molecules such as GZMB, TNF and IFNG in CD8 + T cells, and inhibited the expression of inhibitory molecules such as PD-1, TIM-3 and LAG-3." (PMID 37833287, 2023). "Interestingly, we identified a positive association between the DSE expression and the relative frequency of M1 macrophages, both in normal (16 distinct GTEX tissues) and tumor tissues (five different TCGA tumor types)." (PMID 36009354, 2022). "Dermatan sulfate is considered as a glycosaminoglycan acting as a tumor suppressor and thus DSE may be considered as a tumor suppressor gene." (PMID 20929582, 2010). "Functional validation experiments confirmed that BOP1, CTBP1, DSE, PMSD10, and SRPK1 promote LMS cell migration, invasion, and colony formation, further highlighting their role in tumor progression." (PMID 40963856, 2025). "These functional experiments provide strong evidence that BOP1, CTBP1, DSE, PMSD10, and SRPK1 play key roles in LMS progression, acting as potential therapeutic targets to limit tumor invasion and metastasis." (PMID 40963856, 2025). "In contrast, overexpression of DSE in GL261 cells enhanced these malignant phenotypes and in vivo tumor growth." (PMID 29864158, 2018). "Moreover, overexpression of DSE significantly promoted the invasion of CD4+ and CD8 + T cells into the tumor." (PMID 37833287, 2023). "Other ofCS modification enzymes (DSE, CHST11, and CHST13) were not differentially expressed between normal and tumor samples." (PMID 34966741, 2021).
DSE also shares sentences with these, for which no sentence is quoted: connective tissue disorder (3 papers); hepatocellular carcinoma (2); colon cancer (1); esophagus squamous cell carcinoma (1); lymphoma (1); neuroblastoma (1); oligodendroglioma (1); pulmonary fibrosis (1).